MARCO (macrophage receptor with collagenous structure)
Diseases named in the same sentence as MARCO in open-access papers (continued):
Sharing a sentence is not in itself a finding about the gene and the disease.
influenza infection (10 papers, 2012 to 2021). "MARCO is a scavenger receptor that has been implicated in the clearance of apoptotic cells and in the resolution of long-term lung inflammation; MARCO-deficient mice show early, enhanced development of inflammation in response to infection by influenza." (PMID 34225749, 2021). "Along the same lines, MARCO deficient (MARCO−/−) mice exhibited an early inflammatory response to influenza, characterized by rapid neutrophil influx to the lung, which appear to be beneficial in early resolution of influenza." (PMID 25089703, 2014). "Moreover, the downregulation of MARCO in AM is associated with a decreased clearance and increased susceptibility of Streptococcus pneumoniae after influenza infection." (PMID 32670284, 2020). "Furthermore, changes in MARCO expression have been linked to pneumonia onset after influenza infections." (PMID 33187194, 2020). "Similarly, MARCO can limit inflammatory response as MARCO-deficient mice show an early-enhanced development of inflammation in response to influenza infection." (PMID 26962470, 2015). "Although animal models using MARCO knockout mice strongly associate MARCO with many pulmonary infections, such as pneumonia and influenza, whether polymorphisms in MARCO are associated with susceptibility to infection in humans remains to be determined." (PMID 23617307, 2013). "Administration of recombinant IL-6 rescues macrophages from influenza-induced apoptosis and increases MARCO expression which promotes phagocytosis of bacteria." (PMID 33828999, 2021). "Sun & Metzger found that influenza-induced IFN-gamma impairs bacterial clearance by alveolar macrophages through downregulation of the class A scavenger receptor MARCO." (PMID 33828999, 2021). "For example, MARCO expression on alveolar macrophages decreases during influenza infection." (PMID 32486177, 2020). "We were also not able to verify the decrease of mRNA level of MARCO, another important macrophage scavenger receptor for influenza infections in mice and human cells." (PMID 22396727, 2012).
pulmonary fibrosis (10 papers, 2016 to 2026). Chronic progressive interstitial lung disorder characterized by the replacement of the lung tissue by connective tissue, leading to progressive dyspnea, respiratory failure, or right heart failure. "We describe a previously undefined critical pathogenic role for MARCO+ myeloid cells in skin and lung fibrosis in SSc." (PMID 35104243, 2022). "Moreover, PolyG can inhibit ERS‐related apoptosis and EMT by antagonizing the macrophage receptor MARCO in the lungs and alleviate pulmonary fibrosis caused by silicosis." (PMID 36282897, 2022). "Our study demonstrated that MARCO+ AMs were necessary for the aggravated BLM-induced pulmonary fibrosis in aged mice." (PMID 36934284, 2023). "Additional experiments using siRNA or other means to silence UGRP1 in airway epithelial cells deserve to be performed to show its effects on less CCL6 production from MARCO+ AM and less lung fibrosis." (PMID 36934284, 2023). "Similar to our results, the role of MARCO in apoptosis signaling has been ascertained in silica-induced pulmonary fibrosis, immune-modifying nanoparticle-exposed monocytes, and tumor-associated macrophages." (PMID 37078873, 2023). "In this study, we demonstrated that in the aging lungs, the expression levels of UGRP1 were significantly upregulated, which modulated MARCO+AMs to produce high levels of CCL6, accounting for the susceptibility to pulmonary fibrosis." (PMID 36934284, 2023). "The age-related upregulation of UGRP1 and MARCO+ AMs, involved in the progression of lung fibrosis, was also observed in human lung tissues." (PMID 36934284, 2023). "In previous study, PolyG antagonizes the expression of SR MARCO, and it can attenuate silica‐induced pulmonary fibrosis through inhibition of epithelial‐mesenchymal transition." (PMID 36282897, 2022). "Thus, UGRP1 modulated MARCO+ AMs regarding the age-related lung fibrosis in a CCL6-dependent manner, which is key to establishing optimal targeting for the aging population." (PMID 36934284, 2023). "MARCO modulated the alternative activation of macrophages for their polarization of M2 and the fibrotic responses to lung injury, which was also required for the development of chrysotile-induced pulmonary fibrosis." (PMID 36934284, 2023). "One study demonstrates that human alveolar macrophages collected from patients with asbestosis overexpress MARCO, indicating that this scavenger receptor may contribute to asbestos-induced lung fibrosis." (PMID 37894824, 2023). "MARCO appears to be a potentially novel therapeutic marker that can be targeted to halt the progression of pulmonary fibrosis; it has been shown to promote macrophage polarization to a profibrotic M2 phenotype and precipitate an exaggerated fibrotic response to lung injury in a model of asbestosis." (PMID 35104243, 2022). "Thus, MARCO+ monocytes are potent effector cells of skin and lung fibrosis and can be therapeutically targeted in SSc using PLG nanoparticles." (PMID 35104243, 2022). "Further, in the aggravated fibrotic lungs of aged mice, more MARCO+CCL6+ AMs were observed, indicating the importance of MARCO+ AMs and their production of CCL6 in the development of pulmonary fibrosis." (PMID 36934284, 2023). "Aged MARCO+AMs showed a stronger ability to produce CCL6, and were indispensable for the progression of pulmonary fibrosis." (PMID 36934284, 2023). "Here we show that MARCO+ monocytes are potent effector cells of skin and lung fibrosis, and that PLG nanoparticles both selectively suppress activated MARCO+ monocytes and directly reduce profibrotic cellular signaling." (PMID 35104243, 2022). "Furthermore, MARCO+ AMs aggravated bleomycin-induced pulmonary fibrosis in a CCL6-dependent manner in the aged mice, and blocking MARCO or neutralizing CCL6 significantly inhibited pulmonary fibrosis, similar to the depletion of AMs." (PMID 36934284, 2023).
tuberculosis (9 papers, 2011 to 2018). A chronic, recurrent infection caused by the bacterium Mycobacterium tuberculosis. "In a Chinese Han population, a polymorphism in the scavenger receptor MARCO (macrophage receptor with collagenous structure) was found to be associated with increased risk of tuberculosis." (PMID 29353387, 2018). "According to our study, the TT genotype of rs12998782 in the MARCO gene can increase the risk of tuberculosis." (PMID 28693442, 2017). "In contrast, a polymorphism in human MARCO has been found to be associated with susceptibility to tuberculosis in the Gambian and Han Chinese populations." (PMID 29118429, 2017). "We used a human cellular model to examine how MARCO genotype mediates the immune response; a case–control study to investigate tuberculosis host genetic susceptibility; and a host–pathogen genetic analysis to study host–pathogen interactions." (PMID 27853145, 2016). "In summary, we have demonstrated that genetic variation in a class A scavenger receptor, MARCO, is associated with susceptibility/resistance to tuberculosis in a Gambian population, consistent with previously reported data from a Chinese Han population." (PMID 23617307, 2013). "Herein, we demonstrate that polymorphisms within the human class A scavenger receptor MARCO correlate with susceptibility/resistance to tuberculosis in a Gambian population." (PMID 23617307, 2013). "We studied the frequencies of 25 polymorphisms of MSR1 (SRA) and 22 in MARCO in individuals with tuberculosis (n=1284) and matched controls (n=1349)." (PMID 23617307, 2013). "The MARCO genotypes were preferentially associated with Beijing rather than Indo-Oceanic or Euro-American lineages, which implies MARCO genotype may increase susceptibility to tuberculosis particularly of the Beijing lineage." (PMID 27853145, 2016). "MARCO is a collagen-like molecule; MARCO defects result in susceptibility to tuberculosis." (PMID 27313577, 2016). "Three SNPs in MARCO showed some evidence of association with susceptibility to tuberculosis (p < 0.02), and for one of these, rs7559955, heterozygotes showed reduced risk of tuberculosis (p = 0.008)." (PMID 23617307, 2013). "In both the Chinese Han and Gambian populations, SNPs in intron 1, which we identify as a putative alternative promoter site, are associated with susceptibility to tuberculosis, implying that changes in MARCO function or expression contribute to host defence against tuberculosis." (PMID 23617307, 2013). "Associations between MARCO gene allele frequencies and tuberculosis in Chinese Han population." (PMID 21886847, 2011). "Our study suggested that genetic variants in MARCO gene were associated with pulmonary tuberculosis susceptibility in Chinese Han population, and the findings emphasize the importance of MARCO mediated immune responses in the pathogenesis of tuberculosis." (PMID 21886847, 2011). "Macrophage receptor with a collagenous structure (MARCO) is essential components required for toll like receptor-signaling in macrophage response to Mycobacterium tuberculosis, which may contribute to tuberculosis risk." (PMID 21886847, 2011). "We used a case–control study to determine whether MARCO polymorphisms SNPs rs2278589 and rs6751745 are associated with susceptibility to TB, as macrophages with the heterozygote genotypes of these SNPs displayed reduced phagocytosis of M. tuberculosis ligands." (PMID 27853145, 2016). "Together, our data suggest that TB susceptibility and disease severity in patients with the MARCO AG genotype may be due to impairment of M. tuberculosis phagocytosis." (PMID 27853145, 2016). "We hypothesized that MARCO polymorphisms are associated with phagocytosis, tuberculosis (TB) disease susceptibility and presentation, and infecting lineage." (PMID 27853145, 2016).
tuberculosis (continued). "This provides support for potential consistency of a MARCO association across diverse populations and suggests a role for MARCO, in host defence against tuberculosis, possibly at the level of gene regulation, although further functional studies are warranted." (PMID 23617307, 2013). "Gene polymorphisms of MARCO and CD36 may contribute to tuberculosis risk." (PMID 28693442, 2017). "This may imply that changes in MARCO expression rather than overt changes in structure are key to conferring resistance or susceptibility to tuberculosis." (PMID 23617307, 2013).
pancreatic cancer (8 papers, 2017 to 2025). "Deficiency of MARCO significantly inhibits tumor progression and metastasis in murine models of pancreatic cancer." (PMID 34778091, 2021). "We then analyzed many correlated macrophage biomarkers and the results suggested that MARCO-expressing macrophages are highly associated with poor pancreatic cancer prognosis." (PMID 34778091, 2021). "Additionally, MARCO expression has been linked to reduced survival rates in pancreatic cancer, where it plays a significant role in tumor progression." (PMID 40971385, 2025). "As we observed a generally high MARCO expression in pancreatic cancer and since its expression was connected to survival, this indicates its usefulness for targeting." (PMID 36310582, 2022). "In the current study, we confirm the potential of targeting human MARCO as a next-generation immunotherapy in pancreatic cancer." (PMID 36310582, 2022). "High infiltration of MARCO+ TAMs in tumor was associated with worse OS and DFS in patients with squamous cell carcinoma and pancreatic cancer." (PMID 36686729, 2022). "In the present study, we first confirmed that MARCO expression increased in pancreatic cancer tissues compared with paracancerous control tissues using IHC." (PMID 34778091, 2021). "The univariate and multivariate analyses also demonstrated that high MARCO expression is an independent prognostic marker in pancreatic cancer." (PMID 34778091, 2021). "Crucially, MARCO is highly or exclusively expressed in pancreatic cancer across many types of solid tumors, suggesting its significant role in pancreatic cancer." (PMID 34778091, 2021). "Critically, patients with pancreatic cancer with high MARCO expression exhibited shorter DFS and OS." (PMID 34778091, 2021). "The univariate and multivariate analyses confirmed that combined CD163 and MARCO expression is an independent prognostic marker in pancreatic cancer." (PMID 34778091, 2021). "Nevertheless, the expression of CD163 and MARCO is still a good predictor of pancreatic cancer prognosis." (PMID 34778091, 2021). "Subsequently, we sought to assess the role of MARCO in pancreatic cancer using immunohistochemistry (IHC)." (PMID 34778091, 2021). "Univariate and multivariate analysis revealed that CD163 and MARCO expression was an independent indicator of pancreatic cancer prognosis." (PMID 34778091, 2021). "We observed increased expression of CD163 and MARCO in pancreatic cancer tissues compared with paracancerous tissues." (PMID 34778091, 2021). "Next, we investigated the expression of MARCO in relation to the macrophage marker CD163 in a treatment-naïve pancreatic cancer cohort after surgery (n = 65)." (PMID 34778091, 2021). "Further research into the role of MARCO in periampullary/pancreatic cancer as well as in other intestinal cancer and a broader spectrum of solid cancers is highly warranted." (PMID 28673320, 2017). "Therefore, we first determined that MARCO expression is a biomarker that predicts the progression of pancreatic cancer." (PMID 34778091, 2021). "Finally, we analyzed the expression profiles of CD163 and MARCO in both cancer and paracancerous tissues from patients with pancreatic cancer." (PMID 34778091, 2021). "Moreover, high CD163 and MARCO expression negatively affected the disease-free survival and overall survival rates of patients with pancreatic cancer." (PMID 34778091, 2021). "Furthermore, we observed a large variation in CD163 and MARCO expression in pancreatic cancer tissues among cases, suggesting the heterogeneous expression of these two markers among patients." (PMID 34778091, 2021). "Similarly, patients with pancreatic cancer with high MARCO expression in tumor tissues had a shorter DFS (3.0 months vs 15.5 months, P = 0.0004) and OS (13.0 months vs 24.0 months, P = 0.0003) than MARCO low patients." (PMID 34778091, 2021).
pancreatic cancer (continued). "Although MARCO deficiency significantly inhibited tumor progression and metastasis in a pancreatic mouse model, the role of MARCO in human pancreatic cancer has not been previously reported." (PMID 34778091, 2021). "Furthermore, the highest expression of MARCO in pancreatic cancer suggested that MARCO may play a significant role in this type of cancer." (PMID 34778091, 2021). "Furthermore, we analyzed the combined role of CD163 and MARCO in pancreatic cancer." (PMID 34778091, 2021). "Positive correlation of the number of MARCO+ TAMs with DFS and OS in pancreatic cancer and squamous cell carcinoma.Increase amount of MARCO+TAMs associates with prolonged OS in human HCC." (PMID 36686729, 2022). "However, the role of MARCO in patients with pancreatic cancer remains unclear." (PMID 34778091, 2021). "However, the roles of MARCO-expressing macrophages in human pancreatic cancer remain unclear." (PMID 34778091, 2021). "Deficiency of MARCO was found to significantly inhibit tumor progression and metastasis in a mouse model of pancreatic cancer, and correlation of clinical data showed a strong trend toward poorer survival in patients with high CD163 and MARCO macrophage infiltration." (PMID 39416792, 2024). "In conclusion, high CD163 and MARCO expression in cancer tissues is a negative prognostic marker for pancreatic cancer after surgery." (PMID 34778091, 2021). "As of yet, the prognostic and potential predictive role of MARCO+ TAMs have neither been described in periampullary adenocarcinoma nor in pancreatic cancer." (PMID 28673320, 2017). "MARCO and CD163 mRNA expression in PDAC tissues is a negative prognostic marker for pancreatic cancer after surgery, and the application of anti-bodies against MARCO may present itself as an attractive therapeutic approach to remodel the TME towards susceptibility to immunotherapies." (PMID 39457004, 2024).
glioma (7 papers, 2021 to 2024). A benign or malignant brain and spinal cord tumor that arises from glial cells (astrocytes, oligodendrocytes, ependymal cells). "In glioblastoma, MARCO‐expressing TAMs induce a phenotypic shift toward mesenchymal cellular state of glioma stem cells, promoting both invasive and proliferative activities, as well as therapeutic resistance to irradiation." (PMID 34060699, 2021). "Meanwhile, TGF-β has been experimentally shown to upregulate MARCO expression in M0 BMDMs, joining a host of other studies implicating TGF-β in glioma progression." (PMID 34011400, 2021).
non-small cell lung carcinoma (7 papers, 2019 to 2025). A group of at least three distinct histological types of lung cancer, including non-small cell squamous cell carcinoma, adenocarcinoma, and large cell carcinoma. "SCGB3A2 has been identified as a marker for pulmonary carcinoma in mice and humans, and MARCO has recently been identified as a possible candidate for targeted antibody therapy in non-small cell lung cancer." (PMID 31014259, 2019).
pulmonary tuberculosis (7 papers, 2011 to 2018). A bacterial infection that affects the lungs and is caused by Mycobacterium tuberculosis. "In human pulmonary tuberculosis, some genetic variants of MARCO are associated with susceptibility, while other variants are associated with resistance." (PMID 29033946, 2017). "Our results suggest that MARCO polymorphisms may regulate phagocytosis of M. tuberculosis and thus influence susceptibility to and severity of pulmonary tuberculosis." (PMID 27853145, 2016). "The results also suggest that MARCO genotype and Beijing strains may interact to increase the risk of pulmonary tuberculosis." (PMID 27853145, 2016). "Moreover, genetic variations of MARCO have been associated with susceptibility to pulmonary tuberculosis in a Gambian population." (PMID 24223991, 2013). "Given the strong functional role of MARCO in host immunity against M.tb infection, the genetic component for MARCO might be conferred resistance or susceptibility to pulmonary TB (pTB)." (PMID 21886847, 2011). "By selecting tagging SNPs in MARCO gene, 17 tag SNPs were identified and genotyped in 923 pulmonary tuberculosis patients and 1033 healthy control subjects using a hospital based case-control association study." (PMID 21886847, 2011). "Whether MARCO and CD36 are associated with extra-pulmonary tuberculosis, such as TBM, or intestinal, bone and urinary tuberculosis, needs further investigation." (PMID 28693442, 2017). "In summary, our findings demonstrated that genetic variations in the scavenger receptors, MARCO and CD36, might be associated with susceptibility/resistance to pulmonary tuberculosis in a Chinese Han population." (PMID 28693442, 2017). "MARCO haplotypes analysis in pulmonary tuberculosis cases and controls." (PMID 21886847, 2011).
glioblastoma (6 papers, 2021 to 2024). The most malignant astrocytic tumor (WHO grade IV). "Other studies have identified that MARCO-expressing macrophages, typically present in IDH-wild type glioblastomas only, are associated with worse prognosis." (PMID 38798600, 2024). "More interestingly, this subpopulation of MARCO+ TAMs was found almost exclusively in the IDH-WT glioblastoma, and they exhibited a completely oppositive dynamic in α-PD-1 responders vs. non- responders." (PMID 38239396, 2023). "Unsupervised clustering revealed a pro-tumor subpopulation of bone marrow-derived macrophages characterized by the scavenger receptor MARCO, which is almost exclusively found in IDH1-wild-type glioblastomas." (PMID 34011400, 2021).